TNKS (tankyrase)
Diseases named in the same sentence as TNKS in open-access papers (continued):
Sharing a sentence is not in itself a finding about the gene and the disease.
colon carcinoma (22 papers, 2009 to 2025). "Transferrin receptor (TFRC)‐mediated iron uptake in colon tumors is essential to maintain the activity of tankyrase (TNKS)." (PMID 36703617, 2023). "Mechanistic study revealed that TFRC‐mediated iron uptake in colon tumors is required to maintain the activity of the metal‐dependent TNKS." (PMID 36703617, 2023). "Tankyrase inhibitors have shown promising efficacy in both colon cancer cell lines and colon cancer mouse models that harbour Apc mutations." (PMID 37048063, 2023). "The effect of tankyrase inhibition through WNT/β-catenin inhibition was initially documented in colon cancer cell lines." (PMID 32575464, 2020). "Being important activators of the WNT/β-catenin pathway in colon cancer, tankyrase is a hot topic for drug development and promising clinical data have been reported for several tankyrase-targeting reagents as anti-cancer drugs." (PMID 32268564, 2020). "TKi has been reported to decrease Wnt signaling in colon carcinoma cells, but the effect of tankyrase inhibition of hiPSC-derived S7 cells has to our knowledge never been investigated." (PMID 31139151, 2019). "Wnt/β-catenin signaling perturbation was achieved with E7449 treatment in Wnt-active colon cancer cells and the profiles generated both by western blot and in gene expression studies appeared very similar to that of the selective tankyrase inhibitor XAV939." (PMID 26513298, 2015). "In agreement with effects observed for colon cancer 16,17,20,21,40,44, we found that the TNKS-target AXIN2 was stabilized in all three OS lines evaluated." (PMID 24403055, 2014). "In fact, tankyrase 1 protein levels have been shown to be downregulated in colon cancer, while overexpression of tankyrase 1 has been observed in breast cancer, both of which likely reflect loss of tankyrase 1 PARP activity." (PMID 21037379, 2010). "Aberrant expression of TNKS has been found in cancers and neoplasms, including multiple myeloma, plasma cell leukemia, bladder and colon cancer, and breast cancer." (PMID 19270793, 2009). "Additionally, investigation of human colon carcinoma samples revealed that tankyrase was upregulated and negatively correlated with PTEN expression." (PMID 40134437, 2025). "The successful synthesis, characterization and analysis of inter­molecular inter­actions of aryl­sul­fon­amide Schiff bases have been achieved, alongside their evaluation for inhibitory effects on tankyrase poly(ADP-ribose) polymerase in the context of colon cancer, through in-silico testing." (PMID 38577890, 2024). "Tankyrase poly(ADP-ribose) polymerase, a crucial enzyme involved in DNA repair and the regulation of various cellular processes, has been implicated in the development of colon cancer (Feng & Koh, 2013 ▸; Eisemann & Pascal, 2020 ▸)." (PMID 38577890, 2024). "Reflecting the multitude of their target proteins and cellular functions, TNKS have been implied in a variety of diseases including cancer, including lung cancer, hepatocellular cancer, gastric cancer, breast cancer, and colon cancer." (PMID 30915350, 2019). "Studies were performed to determine if E7449-mediated tankyrase inhibition could affect Wnt signaling in human colon cancer SW480 (Wnt active, APC mutant) cells in vitro." (PMID 26513298, 2015). "Additionally, E7449 inhibited Wnt/β-catenin signaling in colon cancer cell lines, likely through TNKS inhibition." (PMID 26513298, 2015). "Double knockdown of tankyrase 1/2 stabilized PTEN and downregulated AKT signaling, leading to the suppression of colon carcinoma proliferation." (PMID 40134437, 2025). "We wanted to explore the effect of treating GSCs with a small-molecule inhibitor of tankyrase, G007-LK, which has been shown to be a potent modulator of the WNT/β-catenin and Hippo pathways in colon cancer." (PMID 32575464, 2020). "Furthermore, the tankyrase-specific inhibitors JW74 and JW55 influence cell cycle progression and trigger apoptosis and differentiation in osteosarcoma and colon cancer cells." (PMID 40699862, 2025).
colon carcinoma (continued). "Moreover, the synthesized Schiff bases displayed re­marke­able inhibition of tankyrase poly(ADP-ribose) polymerase enzymes, integral in colon cancer, surpassing the efficacy of a standard drug used for the same purpose." (PMID 38577890, 2024). "Conversely, when Axin and Snail levels were increased with tankyrase inhibitor XAV939, cell migratory potential significantly increased, supporting that Axin2 serves tumor progression in colon cancer cells." (PMID 28418862, 2017). "As a major member of the TNKS family, it has been reported that tankyrase 1(TNKS1) were up-regulated in a variety of cancers, including multiple myeloma, plasma cell leukemia, high-grade non-Hodgkin’s lymphomas, breast cancer, colon cancer, and bladder cancer." (PMID 24308762, 2013).
lung carcinoma (22 papers, 2013 to 2025). "Repressing TNKS activity through either genetic or pharmacological approaches antagonized canonical Wnt signalling, reduced murine and human lung cancer cell line growth, and decreased tumour formation in mouse models." (PMID 38898581, 2024). "The role of tankyrases in the development of colon and lung cancer and the use of TNKS inhibitors are better known." (PMID 33910596, 2021). "In patients with lung cancer, tankyrase levels negatively correlate with p-AMPK levels and poor survival." (PMID 31554794, 2019). "To further investigate the role of tankyrase in lung cancer, we generated doxcycline-inducible expression of TNKS1 in LKR13 cells." (PMID 31554794, 2019). "Tankyrase inhibitors have been also shown to sensitise lung cancer cells to EGFR inhibition through a mechanism that involves stabilisation of angiomotins and inhibition of YAP signalling." (PMID 30655555, 2019). "We found that tankyrase is localized to DSBs through its interaction with MERIT40, and pharmacological inhibition of tankyrase sensitized human lung cancer cells to DNA-damaging anticancer agents." (PMID 30533199, 2018). "Among the top 10 differentially expressed genes are others that are linked to pulmonary biology and/or lung cancer (SFTPB, SLIT2, TNKS)." (PMID 28445992, 2017). "We are currently examining the effects of different growth conditions on TNKS inhibitor activity in our lung cancer models." (PMID 23621985, 2013). "Taken together, these findings implicate the use of TNKS inhibitors to target the Wnt pathway to combat lung cancer." (PMID 23621985, 2013). "Repressing TNKS activity through either genetic or pharmacological approaches antagonized canonical Wnt signaling, reduced murine and human lung cancer cell line growth, and decreased tumor formation in mouse models." (PMID 23621985, 2013). "Genetic inhibition of TNKS was independently achieved by use of siRNA or shRNA-mediated knockdown in lung cancer cells." (PMID 23621985, 2013). "Using comprehensive microarray analyses, we found that TNKS were overexpressed in murine lung cancers relative to adjacent normal lung tissues." (PMID 23621985, 2013). "Combined with the in vitro results with the described inhibitors, this suggests a potential for clinical benefit from TNKS inhibition in lung cancer." (PMID 23621985, 2013). "To confirm the expression of TNKS in lung cancer tissues, we examined TNKS immunohistochemistry (IHC) expression in 74 pairs of and found that the expression of TNKS was significantly more highly expressed in lung cancer tissues than in adjacent normal tissues." (PMID 38898581, 2024). "In conclusion, the results suggested that TNKS was abnormally upregulated in lung cancer tissues and cells and was closely related to tumour size and TNM stage, indicating that high expression of TNKS may play an oncogenic role in lung adenocarcinoma." (PMID 38898581, 2024). "XAV-939, a Tankyrase inhibitor, has been shown to promote ferroptosis in lung cancer cells by inducing the down-regulation of SLC7A11, and inhibiting the progression of lung cancer by down-regulating lncRNA MIR503HG, sponging miR-1273c and regulating SOX4 expression." (PMID 37005430, 2023). "In particular, patients with tumours showing aberrant activation of the Wnt/β-catenin pathways (e.g., colorectal and lung cancer) may benefit from tankyrase-targeted therapy." (PMID 32523090, 2020). "Similar TNKS knockdown was achieved in the human lung cancer cell lines A549 and Hop62." (PMID 23621985, 2013). "This study explored the hypothesis that inhibition of TNKS by pharmacological or genetic means would inhibit lung cancer growth in vitro and in vivo in clinically-relevant transgenic mouse models of lung cancer that were previously developed, as reviewed." (PMID 23621985, 2013).
lung carcinoma (continued). "Individual treatments of a well-characterized panel of human and murine lung cancer cell lines with the TNKS inhibitors XAV939 or IWR-1 inhibited cell growth, reduced the activation of a Wnt-responsive lentiviral luciferase construct, and stabilized protein levels of axin and both TNKS." (PMID 23621985, 2013). "Taken together, the findings presented here uncover TNKS as new antineoplastic lung cancer targets." (PMID 23621985, 2013). "Immunoblot analyses of ED1 and ED2 murine lung cancer cell lines and A549 and Hop62 human lung cancer cell lines following treatment with 10 μM of each inhibitor revealed stabilization of TNKS1, as expected due to inhibition of TNKS auto-PARsylation function." (PMID 23621985, 2013). "Antineoplastic consequences of genetic and pharmacologic targeting of TNKS in murine and human lung cancer cell lines were explored, and validated in vivo in mice by implantation of murine transgenic lung cancer cells engineered with reduced TNKS expression relative to controls." (PMID 23621985, 2013). "We sought to validate whether the TNKS inhibitors exerted effects on Wnt signaling in human and murine lung cancer cell lines." (PMID 23621985, 2013). "Wnt-driven cancers such as CRC, HCC, and lung cancers may benefit from Tankyrase inhibitors." (PMID 34639169, 2021). "Because TNKS/2 are accredited upstream regulators of the Wnt pathway, we initially pursued the idea that interception of TNKS/2 activity might prevent Wnt-induced lung cancer cell dissemination." (PMID 26787475, 2016). "Furthermore, the inhibition of the Wnt/β-catenin pathway by tankyrase inhibitors enhances the efficacy of EGFR inhibitor for the treatment of lung cancer, which suggests that tankyrase inhibitors could be used as adjuvant cancer treatments." (PMID 26544726, 2015). "Having established deregulation of Wnt pathway genes and TNKS overexpression in human and murine lung cancer, we next asked whether inhibition of the Wnt pathway with the TNKS inhibitors XAV939, IWR-1 endo, or IWR-1 exo would inhibit growth of murine or human lung cancer cell lines." (PMID 23621985, 2013). "Indeed, a combination of an EGFR and Tankyrase inhibition recently revealed a close functional correlation of both pathways and confirmed the synergistic effect of a dual antagonistic treatment in lung cancer cells." (PMID 23016862, 2013). "And then, TNKS expression in human normal lung bronchial epithelial cells (BEAS‐2B) and four lung cancer cell lines (CALU, SK‐LU‐1, A549, H1975) was determined via RT–qPCR." (PMID 38898581, 2024). "To address the clinical relevance of tankyrase expression and AMPK inactivation in lung cancer, we performed a human lung tumor TMAs for pathologic correlation." (PMID 31554794, 2019). "Our results with the first generation of TNKS inhibitors, XAV939 and the IWR-1 compounds, indicate that they have antiproliferative effects in lung cancer cell lines." (PMID 23621985, 2013). "Single knockdown of either TNKS1 or TNKS2 or dual TNKS knockdowns were growth inhibitory in the ED1, A549, and Hop62 lung cancer cell lines (respectively)." (PMID 23621985, 2013). "Individual treatments of a panel of human and murine lung cancer cell lines with the TNKS inhibitors XAV939 and IWR-1 dose-dependently repressed cell growth and increased cellular axin 1 and tankyrase levels." (PMID 23621985, 2013). "Further, we saw enhanced growth suppression in multiple breast and lung cancer cell lines treated with XAV and Palbociclib, demonstrating a consistent combinatorial effect of TNKS and CDK4 blockade across a broad spectrum of cancer cell lines of epithelial origins." (PMID 31891587, 2019). "All in all, Wnt-dependent activities did not substantially enhance cell motility in lung cancer cell lines, nor were they clearly impacted by TNKS/2 inactivation." (PMID 26787475, 2016).
lung carcinoma (continued). "For example, a critical role for tankyrase and Wnt/β-catenin signaling was identified for maintenance of lung cancer cells during EGFR inhibition and subsequent inhibition of tankyrase significantly enhanced the antitumor activity of EGFR inhibitors in NSCLC cells." (PMID 26513298, 2015).
breast carcinoma (15 papers, 2009 to 2026). "In conclusions, Amot-p130 functions as a tumor suppressor gene in breast cancer, disrupting β-catenin stability by competing with Axin for binding to tankyrase." (PMID 30792381, 2019). "Altogether these results show that inhibiting tankyrase activity either using chemical inhibitors or by abrogation of the expression of tankyrases using siRNA, blocks Wnt transcriptional responses in breast cancer cells." (PMID 23144924, 2012). "Here, we show that XAV939 inhibits tankyrase activity, promotes Axin stabilization and is effective in attenuating Wnt signalling and blocking cell migration in breast cancer cell lines." (PMID 23144924, 2012). "Altogether our results demonstrate that blocking tankyrase activity can inhibit Wnt transcriptional responses and diminish cell migration, growth and colony formation of breast cancer cells." (PMID 23144924, 2012). "The TNKS inhibitor XAV939 has been tested in ovarian cancer, breast cancer, neuroblastoma and hepatocellular carcinoma." (PMID 33910596, 2021). "Tankyrase (TNKS) plays important roles in the malignancy of several cancers such as human lung tumor, breast cancer, and hepatocellular cancer." (PMID 30915350, 2019). "XAV939 (a small molecule inhibitor of Tankyrase) was found to successfully inhibit Tankyrase activity and stabilize Axin in MDA-MB-231 breast cancer cells." (PMID 31416135, 2019). "Breast cancer cell lines with NOS1AP locus amplifications (feature cnaBRCA64 in GDSC) show no differential sensitivity to either porcupine or tankyrase inhibitors compared with breast cancer cell lines without the amplification feature cnaBRCA64." (PMID 36675340, 2023). "For the first time, we demonstrated that a combination of Tankyrase inhibitor i.e., XAV939 and a low dose of paclitaxel treatment could be a potential approach for treating TNBC cancer and carcinogen-induced breast cancer with minimum side effects." (PMID 31416135, 2019). "We show that application of the small molecule tankyrase inhibitor, XAV939 or siRNA-mediated abrogation of tankyrase expression increases Axin1 and Axin2 protein levels and attenuates Wnt-induced transcriptional responses in several breast cancer lines." (PMID 23144924, 2012).
Obesity (9 papers, 2010 to 2023). Accumulation of substantial excess body fat. "Human TNKS, encoding tankyrase 1 (TNKS1), localizes to a susceptibility locus for obesity and type 2 diabetes mellitus (T2DM)." (PMID 32317752, 2020). "The top result rs35433754 (p-value = 0.0017) was in the gene TNKS, previously implicated in extreme early-onset obesity and adult waist circumference." (PMID 28417008, 2017). "The protein product of a candidate risk gene for obesity, TNKS, targets Wnt inhibition, and this gene was significantly associated with hand and knee OA." (PMID 25880085, 2015). "Of interest are the variants in/near five genes (PTER, NPC1, MAF, SDCCAG8 and TNKS/MSRA) that had previously been associated with obesity also using samples of individuals who were extremely overweight." (PMID 21935397, 2011). "We observed that genetic variants in or near FTO, MC4R, TMEM18, SDCCAG8, and TNKS/MSRA were robustly associated with early-onset obesity." (PMID 20421936, 2010). "Nevertheless, these data together suggest that TNKS inactivation provides a potential approach to improve lipid and glucose metabolism in obesity and diabetes." (PMID 32317752, 2020). "Our study unravels a novel molecular mechanism whereby pharmacological inhibition of TNKS in obesity and diabetes enhances oxidative metabolism and ameliorates lipid disorder." (PMID 32317752, 2020). "Here, we addressed the therapeutic potential of G007-LK, a TNKS-specific inhibitor, for obesity and T2DM." (PMID 32317752, 2020). "In sum a strong impact of the detected mutations in TNKS and SDCCAG8 on obesity cannot be derived from our data." (PMID 26828654, 2016). "In humans, TNKS (the gene encoding tankyrase 1, TNKS1) localizes to chromosome 8p23.1, a susceptibility locus for T2DM, and variants of TNKS associate with early-onset obesity." (PMID 32317752, 2020). "This highlights inhibition of TNKS as a potential pharmacotherapy for obesity and T2DM." (PMID 32317752, 2020). "However, the variants we detected were too infrequent for meaningful obesity association analysis (SDCCAG8 [Thr398Met], TNKS [Pro275Ala], MSRA [Arg6GlufsX88], [Asp142Tyr], [Gly187Ser]) or showed no obesity association (SDCCAG8 [Glu378Asp], TNKS [Gly237Ala]; MSRA [Thr88Met],)." (PMID 26828654, 2016).
osteosarcoma (9 papers, 2014 to 2025). A usually aggressive malignant bone-forming mesenchymal neoplasm, predominantly affecting adolescents and young adults. "IWR-1, a tankyrase inhibitor, can hamper the expression of key stem markers in osteosarcoma, impair osteosarcoma CSC self-renewal and enhance doxorubicin sensitivity by affecting β-catenin translocation in vivo." (PMID 33276800, 2020). "IWR-1, a tankyrase inhibitor, can impair osteosarcoma CSC self-renewal, hamper the expression of key stem markers in osteosarcoma, and increase doxorubicin sensitivity in vivo by inhibiting β-catenin translocation." (PMID 32456660, 2020). "Therefore, the inhibition of the Wnt/β-catenin signaling pathway with tankyrase inhibitors, JW24 or IWR-1, promotes capase-3-mediated apoptosis in association with reduced cell proliferation in osteosarcoma." (PMID 34062831, 2021). "Moreover, the tankyrase inhibitor JW74, showed stabilization of the tankyrase-target Axin2, down-regulation of the nuclear fraction of β-catenin and reduced in vitro cell growth in osteosarcoma cell lines." (PMID 24842792, 2014). "As an example, the tankyrase inhibitor JW24 decreased β-catenin nuclear accumulation and reduced osteosarcoma cell growth." (PMID 34062831, 2021). "Furthermore, the tankyrase-specific inhibitor, JW74 and JW55 affects cell cycle progression and induced apoptosis and differentiation in osteosarcoma and colon carcinoma cells, respectively." (PMID 33276800, 2020).
diabetes (7 papers, 2016 to 2023). "Interestingly, C12orf43, TBL1X and TNKS were significantly associated with diabetes or hypertension-related phenotypes in the UK Biobank." (PMID 37239390, 2023). "We propose that autologous or cell-banked transplantable progenitors derived from tankyrase inhibitor-regulated N-hiPSC will more effectively reverse the epigenetic pathology that drives diseases such as diabetes." (PMID 32139672, 2020). "Boswellia triterpenoids targeted the cancer-relevant proteins (poly(ADP-ribose) polymerase-1, tankyrase, and folate receptor β), inflammation-relevant proteins (phospholipase A2, epoxide hydrolase, and fibroblast collagenase), and the diabetes target 11β-hydroxysteroid dehydrogenase." (PMID 30200355, 2018). "We propose that reprogramming of patient donor cells to tankyrase/PARP inhibitor-regulated N-hiPSC may more effectively erase epigenetic aberrations sustained from chronic diseases such as diabetes, and improve their utility in subsequent regenerative therapies." (PMID 32139672, 2020).